FOS (Fos proto-oncogene, AP-1 transcription factor subunit)
Diseases named in the same sentence as FOS in open-access papers (continued):
Sharing a sentence is not in itself a finding about the gene and the disease.
periodontitis (18 papers, 2019 to 2026). An acute or chronic inflammatory process that affects the tissues that surround and support the teeth. "In the complex pathological milieu of periodontitis, FOS is likely implicated in the initiation and progression of the disease through multiple mechanisms." (PMID 41459503, 2025). "FOS is implicated in periodontitis progression acting via the regulation of T-cell receptor (TCR) signaling." (PMID 33777111, 2021). "We also identified three “master” immunosuppression genes, PECAM1, FCGR3A, and FOS, as candidate genes central to immune suppressive pathogenic mechanisms in periodontitis." (PMID 33777111, 2021). "More importantly, dysregulation of FOS may be linked to sustained bone destruction in periodontitis." (PMID 41459503, 2025). "In summary, FOS likely contributes to the pathogenesis of periodontitis by modulating osteoclast differentiation and associated signaling pathways, providing a new direction for further exploration of the molecular mechanisms underlying periodontal bone destruction." (PMID 41459503, 2025). "This provides new insights into their potential mechanisms of action in periodontitis and offers a theoretical basis for developing multi-target therapeutic strategies aimed at the FOS signaling axis." (PMID 41459503, 2025). "Although no studies have directly reported specific interactions between FOS and these compounds in periodontitis, molecular docking has demonstrated their favorable binding characteristics with the FOS protein." (PMID 41459503, 2025). "Experimental validation is required to confirm the actual binding between these compounds and FOS, as well as to assess their interventional effects in cellular models of periodontitis." (PMID 41459503, 2025). "Additional genes encoding FOS and JUN family members (JUNB, FOSB, FOSL1) were significantly downregulated in periodontitis." (PMID 41124422, 2025). "The Healthy group showed significantly higher nuclear FOS expression in the suprabasal layer of the epithelium than the Periodontitis group." (PMID 41124422, 2025). "The results revealed that both odanacatib and LHVS exhibit high binding affinity with FOS (binding energies < -5.0 kcal/mol), suggesting their potential to modulate FOS-related signaling pathways in the treatment of periodontitis." (PMID 41459503, 2025). "Expression of FOS was downregulated in total periodontitis tissues compared with total control tissues [ratio of mean expression (RME) = 0.23, P-value = 0.03]." (PMID 36090248, 2022). "Expression of FOS was downregulated in total periodontitis tissues compared with total control tissues (RME = 0.23, P-value = 0.03) and in affected tissues obtained from women compared with female control tissue (RME = 0.12, P-value = 0.03)." (PMID 36090248, 2022). "Expression of FOS was downregulated in total periodontitis tissues compared with total control tissues and in affected tissues obtained from women compared with female control tissue." (PMID 36090248, 2022). "Three “master” immunosuppression genes, PECAM1, FCGR3A, and FOS were identified as candidates pivotal to immunosuppressive mechanisms in periodontitis." (PMID 33777111, 2021). "PECAM1, FCGR3A, and FOS emerged as high-value biomarkers and candidate therapeutic targets for periodontitis." (PMID 33777111, 2021). "We not only identified a novel set of ISR-related biomarkers—BTG2, DERL3, FOS, HSPA13, and YOD1—but also revealed their potential associations with periodontitis-specific pathological features, such as osteoclast differentiation and the RANKL/OPG signaling pathway." (PMID 41459503, 2025). "In addition, during periodontitis, increased expression levels of the FOS and JUN genes were observed in CD4+ T-cells, indicating their importance in cell activation." (PMID 37834287, 2023).
periodontitis (continued). "The central finding of our study is the identification of three distinct immunosuppression genes, PECAM1, FCGR3A, and FOS, which could be potentially high-value biomarkers or candidate therapeutic targets for periodontitis." (PMID 33777111, 2021). "As shown in the Venn diagram, three significant DEGs, Platelet Endothelial Cell Adhesion Molecule (PECAM) 1, Fc Gamma Receptor (FCGR) 3A, and FOS were found intersecting and considered as potentially most robust immunosuppression genes related to periodontitis." (PMID 33777111, 2021). "In the IL-17 Signaling pathway, identified as the most suppressed CP, FOS, JUN, Matrix Metallopeptidase 13 (MMP-13), and C-C Motif Chemokine Ligand 20 (CCL20) were downregulated in periodontitis tissues (Log2FC<-1.5)." (PMID 41124422, 2025). "In this study, BTG2, DERL3, FOS, and HSPA13 were significantly upregulated, and YOD1 was significantly downregulated in the gingival tissues of periodontitis patients, confirming their detectable presence locally." (PMID 41459503, 2025). "Transcriptomic network analysis has identified transcription factors (TFs), including NF-κB (NFKB1/RELA), AP-1 (FOS/JUN), and STAT3, as master regulators in periodontitis, highlighting their recent relevance." (PMID 41050338, 2025). "In this study, seven genes (CD19, CXCR4, FABP4, FOS, IGHD, IL2RG, and PPBP) were significantly up-regulated in periodontitis samples." (PMID 39917706, 2024). "The integration of GWAS with the eQTLs of these genes from the peripheral blood prioritized 6 genes, including MCUR1, RAP2A, FOS, PANX1, NFIX and WNK1, in the pathogenesis of periodontitis-related T2D." (PMID 38811930, 2024). "A total of 7 genes (CD19, CXCR4, FABP4, FOS, IGHD, IL2RG, and PPBP) were upregulated in periodontitis samples." (PMID 39917706, 2024). "Recent studies utilizing single-cell sequencing (scRNA) technology in the periodontal tissues of periodontitis-affected or healthy individuals revealed the differential expression of the BCL6, FOS, and JUN MRs during osteoclastogenesis." (PMID 37834287, 2023). "In contrast, 8 MRs (ESR1, CEBPB, FOS, BCL6, E2F1, SPI1, STAT3, and ETS1) were consistently expressed at higher levels (U test statistic between 10 and 16) in the periodontitis condition." (PMID 37834287, 2023). "Periodontitis in adults resulted in decreased levels of CSNK1D, RORA, CLOCK, DBP, NR1D1, ID2, and PER3 and a substantial increase in expression of FOS." (PMID 36472983, 2022). "A deep learning-based autoencoder predicted FOS and JUN to be critical immunosuppression genes and mediate immune suppression in periodontitis." (PMID 36045361, 2022). "Five mRNAs, i,e., FOS, JUN, KLF2, WIF1, and THBS1, for further validation via RT-qPCR on 15 periodontitis and 15 healthy gingivae samples." (PMID 36045361, 2022). "JUN, FOS, KLF2, THBS1 and WIF1 were identified as key regulator in periodontitis and validated to be highly expressed in IPT through RT-qPCR." (PMID 36045361, 2022). "In this study, we assessed the expression of FOS, ITPR, RCAN1, and RGS2 genes in the circulation and affected tissues of patients with periodontitis compared with normal controls." (PMID 36090248, 2022). "Three transcription factors, FOS, MEF2C, and USF2, were identified as related to the regulation of the crosstalk genes and were also found to be dysregulated in chronic periodontitis." (PMID 33869630, 2021). "Furthermore, PCA analysis demonstrated that the expression values of the 10 critical autophagy genes can well distinguish periodontitis and healthy samples, suggesting autophagy gene FOS may make the greatest contribution to distinguish periodontitis samples from healthy." (PMID 33289699, 2020). "MCUR1, RAP2A, FOS, PANX1, NFIX and WNK1 may play important roles in the pathogenesis of periodontitis-related T2D, shedding light on the development of potential drug targets." (PMID 38811930, 2024).
periodontitis (continued). "The integration of GWAS with the expression quantitative trait locis of these genes from the peripheral blood genetically prioritized 6 candidate genes, including 2 risk genes (RAP2A, MCUR1) and 4 protective genes (WNK1, NFIX, FOS, PANX1) in periodontitis-related T2D." (PMID 38811930, 2024). "The analysis of the transcriptomic datasets of human periodontitis (GSE16134 and GSE10334) and the immunosuppression genes by deep learning-based autoencoder techniques suggested that FOS and JUN were downregulated transcription factors with possible roles in periodontitis." (PMID 38241313, 2024). "To test this hypothesis, we designed this study and measured the expression levels of FOS, ITPR, RCAN1, and RGS2 genes in the affected tissues and the circulation of patients with periodontitis vs. appropriate controls." (PMID 36090248, 2022). "Of the top 10 hub TFs, six “leader” immunosuppressive TF-target DEGs with plausible literature evidence were identified as key to periodontitis pathogenesis and included the down-regulated TFs (NFKB1, FOS, and JUN), as well as up-regulated TFs (HIF1A, STAT5B, and STAT4)." (PMID 33777111, 2021). "Furthermore, MCUR1, RAP2A, FOS, PANX1, NFIX and WNK1 were verified to play important roles in the pathogenesis of periodontitis-related T2D, shedding light on the discovery of potential drug targets for periodontitis patients to prevent T2D." (PMID 38811930, 2024). "Importantly, ATF3, FOS, and JUN, that function in Tumor Microenvironment and PI3K Signaling in B Lymphocytes pathways, were exclusively downregulated in periodontitis in the non-diabetic patients." (PMID 38241313, 2024).
schizophrenia (18 papers, 2011 to 2026). A major psychotic disorder characterized by abnormalities in the perception or expression of reality. "On the other hand, some alleles of the FOS gene have been found to play a protective role, whereas others seem to be a risk factor for SZ, which has been connected to schizophrenia-related alterations in synaptic plasticity." (PMID 34327202, 2021). "Our study, which analyzed FOS gene expression in peripheral and CNS tissues, provides a new window into the molecular changes underlying schizophrenia pathogenesis." (PMID 30967896, 2019). "Additionally, CSI-Genomescape predicts that rs1869901, a variant associated with schizophrenia, impacts binding of FOS•CEBPE by altering a TRE-CAAT site." (PMID 28186491, 2017). "Unlike previous studies, which analyzed peripheral or CNS samples only from schizophrenia patients, we identified FOS expression changes in different tissues." (PMID 30967896, 2019). "To further address the role of FOS in schizophrenia pathogenesis, we analyzed human postmortem dorsolateral prefrontal cortex samples and brain tissues of a schizophrenia 22q11-deletion mouse model." (PMID 30967896, 2019). "The alteration of FOS expression in peripheral and CNS tissues of schizophrenia indicates that this gene is sensitive for schizophrenia." (PMID 30967896, 2019). "The analysis of the top 10 DEGs in schizophrenia and healthy samples revealed that FOS and FOSB (which are involved in the AMPH addiction pathway), were significantly up-regulated in schizophrenia fibroblast samples." (PMID 30967896, 2019). "The results from two GEO datasets GSE62333 and GSE73129 demonstrated up-regulated expression of FOS in fibroblast and lymphoblast samples from schizophrenia patients, which were involved in the AMPH pathway." (PMID 30967896, 2019). "FOS and FOSB, which are implicated in the amphetamine addiction pathway, were up-regulated in schizophrenia fibroblast samples." (PMID 30967896, 2019). "Previous research has shown that NMDA receptor antagonist-induced and AMPH-induced pharmacological animal models of schizophrenia can up-regulate FOS gene expression." (PMID 30967896, 2019). "The results showed a significant difference of FOS expression between schizophrenia and control lymphoblast samples." (PMID 30967896, 2019). "A previous study of GEO datasets GSE62333 also reported the up-regulation of FOSB and FOS in the fibroblasts of schizophrenia patients and mainly focused on EGR1 and other genes as biomarkers for disease diagnosis." (PMID 30967896, 2019). "FOS was down-regulated in human postmortem dorsolateral prefrontal cortex samples and brain tissues of a schizophrenia 22q11-deletion mouse model." (PMID 30967896, 2019). "We observed that FOS expression was highly up-regulated in schizophrenia group of dataset GSE62333 which was then validated in another dataset GSE73129." (PMID 30967896, 2019). "To measure the predictive value of FOS in the datasets we used, ROC curves for FOS expression in schizophrenia samples and control samples were performed." (PMID 30967896, 2019). "To conclude, our results indicate that FOS was significantly up-regulated in schizophrenia fibroblast and lymphoblast samples." (PMID 30967896, 2019). "This suggested that FOS may have some connection with AMPH addiction pathway in schizophrenia samples." (PMID 30967896, 2019). "The signatures we identified are consistent with current hypotheses of molecular dysfunction in schizophrenia, including alteration of the FOS gene and involvement of the AMPH addiction pathway." (PMID 30967896, 2019). "Thus, our results support previous findings and reveal a previously unrecognized pathway connected with FOS in the pathogenesis of schizophrenia." (PMID 30967896, 2019). "The results revealed that FOS was acceptable as a biomarker for schizophrenia and may be involved in schizophrenia pathogenesis." (PMID 30967896, 2019). "Among the top 10 DEGs, FOS was most closely related to schizophrenia pathogenesis." (PMID 30967896, 2019).
schizophrenia (continued). "These combined results suggested FOS is acceptable as a biomarker of schizophrenia." (PMID 30967896, 2019). "FOS exhibited predictive value for schizophrenia patients in these datasets." (PMID 30967896, 2019). "FOS was up-regulated in schizophrenia samples and is a recognized marker of neural activation." (PMID 30967896, 2019). "Besides, FOS is thought to play an important role in the pathophysiology of schizophrenia." (PMID 30967896, 2019). "Detection of FOS in blood samples may be helpful for schizophrenia diagnosis." (PMID 30967896, 2019). "Our analysis demonstrated high FOS expression in non-neural peripheral samples and low FOS expression in brain tissues of schizophrenia patients compared with healthy controls." (PMID 30967896, 2019). "Therefore, we further explicate the roles of the FOS gene and the AMPH pathway in the pathogenesis of schizophrenia." (PMID 30967896, 2019). "FOS and AMPH-related genes may thus represent novel biomarkers for diagnosis of schizophrenia in clinical practice." (PMID 30967896, 2019). "Further exploration using postmortem human brains and 22q11-deletion mouse brain samples suggested that FOS is up-regulated in non-neural peripheral samples and down-regulated in brain tissues of schizophrenia patients compared with those of healthy controls." (PMID 30967896, 2019). "Transcription factor activity analysis also revealed a panel of seventeen transcription factors with more significant activity in males; NFKB1, FOS, and KLF6 had been linked to schizophrenia previously, although none had been specifically linked to male schizophrenic patients." (PMID 39068467, 2024).
glioblastoma (16 papers, 2010 to 2026). The most malignant astrocytic tumor (WHO grade IV). "In both glioblastoma cell lines, depletion of FOS, NFKB inhibitor alpha (NFKBIA) and EGFR resulted in similar basal clonogenic and clonogenic radiation survival compared to Lpd depletion." (PMID 34771501, 2021). "To determine the role of EMP3 on EMT in glioblastoma, we first performed a correlation analysis of gene expression, which showed that EMP3 was positively correlated with VIM, FOS, SNAI2 and TWIST1 (p < 0.001, R: VIM: 0.754, FOS:0.382, SNAI2: 0.498, TWIST1: 0.605)." (PMID 38229014, 2024).
Osteoblastoma (16 papers, 2018 to 2025). A rare benign bone-forming neoplasm usually arising from the spine. "FOS is a gene that codes for a protein and is linked to diseases such as osteoblastoma and congenital systemic lipodystrophy." (PMID 37305753, 2023). "Previous studies found that the FOS gene is a candidate risk gene for several kinds of cancer such as liver cancer, skin cancer, and osteoblastoma." (PMID 36569220, 2022). "Osteoblastoma is a bone‐forming tumour that harbours mutations affecting FOS, or more rarely its paralogue FOSB, in a high proportion of cases." (PMID 32542935, 2020). "The exact frequency of osteoblastomas with FOS or FOSB mutations varies depending on the methodology applied." (PMID 32542935, 2020). "Taken together, we show that NF2 loss characterises a subgroup of osteoblastomas, distinct from FOS‐rearranged cases." (PMID 32542935, 2020). "Our main finding was complete loss of the NF2 gene in a subgroup of non‐FOS‐rearranged, preferentially epithelioid osteoblastomas." (PMID 32542935, 2020). "Extending our findings into a cohort of 55 cases, using FISH and immunohistochemistry, provide evidence of ubiquitous mutation of FOS or FOSB in osteoblastoma and osteoid osteoma." (PMID 29858576, 2018). "Here, the authors report rearrangement of FOS and its paralogue FOSB in osteoblastoma and osteoid osteoma, revealing human bone tumours that are defined by mutations of FOS and FOSB." (PMID 29858576, 2018). "Besides methylation and copy number profiling, immunostaining of FOS as well as the detection of a FOS rearrangement by FISH represent robust diagnostic tools as 85% of our osteoblastomas were shown to be positive in at least one of these in-situ analyses." (PMID 35347251, 2022). "FOS rearrangements in osteoid osteoma and osteoblastoma for example lead to an overexpression of the FOS protein that can be detected immunohistochemically." (PMID 38231260, 2024). "FOS gene rearrangements are found in epithelioid hemangioma and osteoid-osteoma/osteoblastoma (with c-FOS overexpression), demonstrating the important role of this gene in not only normal physiological processes but also pathological conditions." (PMID 39677262, 2024). "We next delved into the three FOSL1 wild‐type and immunonegative cases of desmoplastic fibroblastoma and found that two of these contained breakpoints in the final exon of FOS, identical to the recurrent alterations that typify osteoblastoma." (PMID 36426824, 2023). "Rearrangements of the transcription factors FOS and FOSB have recently been identified as the genetic driver event underlying osteoid osteoma and osteoblastoma." (PMID 35347251, 2022). "Consistent FOS expression was identified in 85% (n = 40) of osteoblastomas / osteoid osteomas, whereas 15% were immunohistochemically negative (n = 6) or not evaluable (n = 1)." (PMID 35347251, 2022). "In contrast to these observations, a small series of six epithelioid osteoblastomas of the jaws were described as all showing a strong nuclear FOS staining." (PMID 35347251, 2022). "Although highly desirable, the molecular characterization of osteoblastomas relying on the expression of FOS/FOSB by IHC can be misleading in some cases." (PMID 35347251, 2022). "FOS gene rearrangements were investigated by immunostaining of the FOS protein (n = 45 osteoblastomas, n = 2 osteoid osteomas) and FISH of the FOS gene (n = 25)." (PMID 35347251, 2022). "Both other cases, however, were immunohistochemically strongly positive for FOS and co-localized with conventional osteoblastoma when evaluated by methylation-based clustering." (PMID 35347251, 2022). "Cementoblastoma now has some molecular updates that it shows c-FOS overexpression and harbors the same FOS rearrangement as osteoblastoma, a histologic mimicker." (PMID 35578902, 2022). "Interphase FISH for FOS was performed for all osteoid osteomas and osteoblastomas, which was successful in 31/43 cases (27 paraffin, 4 frozen sections)." (PMID 31768625, 2020).